FBP1 (fructose-bisphosphatase 1)
Diseases named in the same sentence as FBP1 in open-access papers (continued):
Sharing a sentence is not in itself a finding about the gene and the disease.
breast carcinoma (continued). "A decrease in FBP1 expression also promotes interactions between β-catenin and T-cell factor, resulting in an increase in the CSC-like characteristics of breast cancer cells." (PMID 35740522, 2022). "In breast cancer, SNAI1 controls the inhibition of fructose-1,6-bisphosphatase 1 (FBP1) in order to stimulate glycolysis." (PMID 35736645, 2022). "PE‐Lap (FBP1, ITGA11, TRIM68, BCAT1, ZNF780A, UTP20 and GRB7) predicted outcomes of breast cancer patients treated with lapatinib." (PMID 34766125, 2020). "FBP1 knockdown efficiency was validated in MCF-7 cells, and the data showed that FBP1 negatively mediated endogenous p65 protein levels in breast cancer cells." (PMID 32754266, 2020). "They found that FBP1 inhibits STAT3-dependent PD-L1 transcription, a finding that is consistent with our discovery in breast cancer." (PMID 32754266, 2020). "In basal-like breast cancer, an aggressive subtype containing abundant EMT features, the Snail-G9a-Mnmt1 complex was shown to directly bind to the FBP1 promoter, leading to DNA methylation and transcriptional silencing of the gene." (PMID 31181802, 2019). "In breast cancer, negative regulation of HIF-1α by FBP1 results in decreased growth, migration, glucose consumption, and lactate production." (PMID 31552162, 2019). "G9a, which catalyzes H3K9 methylation, has been reported to epigenetically silence fructose-1,6-bisphosphatase 1 (FBP1), leading to enhanced aerobic glycolysis in breast cancer." (PMID 30922330, 2019). "Treatment of cells with 5AZA resulted in a significant increase in the expression of FBPase mRNA in breast cancer, gastric cancer and lung cancer, while treatment with sodium butyrate, SAHA and LBH589 upregulated FBP1 protein and mRNA expression in HCC." (PMID 29556139, 2018). "Mechanically, promotion of breast cancer progression by HMGB2 directly and significantly correlated with activation of LDHB expression and inactivation of FBP1 expression." (PMID 29463261, 2018). "HMGB2 expression plays important roles in breast cancer progression by regulating proliferation and the Warburg effect by transcriptional regulation of LDHB and FBP1 activity." (PMID 29463261, 2018). "FBP1 also suppresses PKM2 activation and increases the activity of mitochondrial complex I to hinder breast cancer cell proliferation." (PMID 28240261, 2017). "Furthermore, FBP-2 and FBP-1 were found to attenuate soft tissue sarcomas (STS) and breast cancer, respectively." (PMID 33256814, 2020). "These epigenetically silenced genes include epithelial-associated cell adhesion molecule, E-cadherin, and glycolytic antagonist, fructose-1,6-biphosphatase (FBP1), which contribute to EMT development and the switch to glycolytic metabolism in breast cancer cells." (PMID 31552162, 2019). "FBP1 over-expression was found to be a common event, irrespective of histological type, in cell lines and human breast cancer." (PMID 29556139, 2018). "FBP1 suppression resulted in an increased cancer stem cell (CSC)-like phenotype and tumourigenesis by enhancing the interaction of β–catenin with T-cell factor in basal-like breast cancer cells." (PMID 30429463, 2018). "The same was demonstrated in renal clear cell carcinoma cell lines and basal-like breast cancer, in which DNMTs were recruited by Snail through G9a and SUV39H1, two HMTs that establish H3K9me3, leading to aberrant methylation of FBP1 promotor." (PMID 30356832, 2018). "It has been studied that loss of FBP1 by snail-mediated repression could provide metabolic advantages in basal-like breast cancers (BLBC); snail, a transcription factor, binds directly to the E-boxes present in the promoter of the FBP1 gene, repressing its transcription by methylation." (PMID 39997396, 2025).
breast carcinoma (continued). "However, the posttranscriptional modification of noncanonical FBP1 has never been elucidated in breast cancer." (PMID 32754266, 2020). "However, the underlying mechanisms of post-transcriptional modification for the non-canonical function of FBP1 remain elusive in breast cancer." (PMID 32754266, 2020). "Our findings further suggest that PIM2-mediated non-canonical FBP1 phosphorylation may be targeted in breast cancer therapies." (PMID 32754266, 2020). "The detailed mechanisms of antitumor function of FBP1 are still remaining to be unclear; it has elucidated that Snail-G9a-Dnmt1 complex is critical for FBP1 silence, which promoted the interaction of β-catenin and TCF and played an important role in EMT transformation in basal-like breast cancer." (PMID 29984231, 2018). "Finally, we assessed the level of the fructose 1,6-biphosphatase (FBP1) gluconeogenic enzyme, which has been shown to contribute to the characteristics of CSCs in basal-like breast cancer and found that the level of FBP1 was higher in CSCs than in non-CSCs." (PMID 29190956, 2017). "FBP1 was also found to be negative correlated with HIF1α activity in HCC and breast cancer." (PMID 29556139, 2018). "Unlike FBP1, we show that inhibition of PDK4 alone is sufficient to induce EMT, and ectopic expression of PDK4 could partially prevent TGFβ-induced EMT, although PDK4 is not differentially expressed between the basal and luminal subtypes of breast cancer (data not shown)." (PMID 25379179, 2014).
hepatocellular carcinoma (46 papers, 2011 to 2025). A malignant tumor that arises from hepatocytes. "FBP1 is abundantly expressed in the majority of hepatocellular carcinoma tumors and has been implicated in tumor development." (PMID 25487856, 2014). "For example, fructose-1,6-bisphosphatase 1 (FBP1) acts as a protein phosphatase to dephosphorylate TERT S227, inducing cell senescence, and its deficiency promotes tumor growth in hepatocellular carcinoma." (PMID 41213904, 2025). "In hepatocellular carcinoma (HCC), elevated HMGB1 released from gluconeogenic enzyme fructose 1,6-bisphosphatase (FBP1)-deficient hepatocytes triggers HSCs activation." (PMID 40761743, 2025). "FBP1 inhibited glycolysis in hepatocellular carcinoma cells, and its expression was regulated by FOXP2 which reduced the KDM5A-mediated loss of H3K4me3 from FBP1 promoter region." (PMID 40940894, 2025). "In contrast to normal hepatocytes, hepatocellular carcinoma (HCC) cells exhibited greatly reduced nuclear translocation of FBP1 upon glucose deprivation." (PMID 36857532, 2023). "In gastric cancer, colon cancer and hepatocellular carcinoma, the expression of FBP1 is downregulated, and its deletion is related to the poor prognosis of clear cell renal cell carcinoma and hepatocellular carcinoma." (PMID 36237339, 2022). "Meng and his colleagues reported that HSF2 regulate aerobic glycolysis in hepatocellular carcinoma through the suppression of fructose-1,6-biphosphatase 1 (FBP1)." (PMID 36430241, 2022). "The low expression of FBP1 promoted the invasion of hepatocellular carcinoma cells through the Warburg effect." (PMID 33564363, 2021). "On the pathophysiological mechanism of hepatic stellate cell contribution in hepatocellular carcinoma, a recent study revealed that loss of the gluconeogenic enzyme FBP1 (fructose 1,6-bisphosphatase 1) promotes HCC development through crosstalk of senescent hepatic stellate cells and hepatocytes." (PMID 34572959, 2021). "Similar to the expression of FBP1 in hepatocellular carcinoma, our current study showed that FBP1 was also decreased in ccRCC tissues compared with peritumor tissues, which is consistent with previous studies." (PMID 30723389, 2019). "In hepatocellular carcinoma and colon cancer, forced FBP1 expression was found to increase the number of G2–M phase cells but decrease the number of S phase cells." (PMID 29556139, 2018). "Hepatocellular carcinoma (HCC) exhibiting low expression of FBP1 had a highly malignant phenotype, including large tumour size, poor differentiation, and advanced tumour stage, as well as vascular cell invasion and a high pathological grade (stages III–IV)." (PMID 29556139, 2018). "It has been reported previously that TRIM28 functions as an E3 ligase of FBP1 in Hepatocellular carcinoma." (PMID 30201002, 2018). "High expression of TRIM28 increased glucose consumption and lactate production by promoting FBP1 degradation in hepatocellular carcinoma and resulted in stimulation of cancer cells growth both in vitro and in mice model." (PMID 28851455, 2017). "In a mouse xenograft transplantation model, knockdown of FBP1 in hepatocellular carcinoma cells resulted in high sensitivity to cell death treatment, lowered proliferation, and tumor formation." (PMID 25487856, 2014). "Dramatic decrease of PEPCK, FBP1 and G6Pase gene expression was observed in hepatocellular carcinoma (HCC) developed in a mouse model and in the majority of primary human HCCs." (PMID 23755305, 2013). "In addition to FBP1 deletion significantly affecting the progression of hepatocellular carcinoma and renal carcinoma, it is also down-regulated in gastric, pancreatic, colorectal, breast, prostate, bile duct, esophageal, lung, and ovarian cancers." (PMID 40100307, 2025). "For example, promoter methylation may also participate in regulating FBP1 levels in skin as FBP1 promoter exhibits higher methylation in hepatocellular carcinoma than in normal liver tissues." (PMID 38834617, 2024).
hepatocellular carcinoma (continued). "As described, one of them is that HSF2 contributes to the hepatocellular carcinoma survival as a part of the Wnt/β-catenin/TCF pathway, and the other one is that HSF2 suppresses FBP1 and upregulates aerobic glycolysis essential for hepatocellular carcinoma growth." (PMID 36430241, 2022). "Also, in vitro data in other tumor entities such as prostate, gastric and hepatocellular cancer found FBP1 gene silencing, leading to promotion of epithelial to mesenchymal transition, invasion, and metastasis." (PMID 35477823, 2022). "Similarly, in human hepatocellular carcinoma and colon cancer promoter hypermethylation of FBP1 inhibited the tumor-suppressive effect of this enzyme." (PMID 35477823, 2022). "Interestingly, we found long-term survival of HBV leads to down-regulated expression levels of F11 and FBP1 mRNAs but up-regulated PSRC1 mRNA in HBV-replicating hepatocellular carcinoma cell lines." (PMID 36212461, 2022). "FBP1 was reported as a metabolic tumor suppressor factor in hepatocellular carcinoma Cancer Discovery (2020), and the deletion of FBP1 could promote tumor growth by affecting crosstalk between hepatocyte metabolism and HSC senescence." (PMID 35127693, 2021). "Additionally, inhibiting far upstream element binding protein 1 (FBP1) has been shown to increase hepatocellular carcinoma (HCC) sensitivity towards apoptotic stimulation, which therefore inhibits cell proliferation." (PMID 23946791, 2013). "FBP1 is considered a tumor suppressor gene in gastric cancer cells and down-regulation of FBP1 that is mediated by promoter hypermethylation is found in human hepatocellular carcinoma and colon cancer." (PMID 23620736, 2013). "FBP1 was lowly expressed in 80% (8/10) human hepatocellular carcinoma, 66.7% (6/9) liver cancer cell lines and 100% (6/6) colon cancer cell lines, but was higher in paired adjacent non-tumor tissues and immortalized normal cell lines, which was well correlated with its promoter methylation status." (PMID 22039417, 2011). "In addition, previous studies have shown that high FBP1 expression inhibits tumor growth by hindering epithelial-mesenchymal transition (EMT) 33, and degradation of FBP1 promotes tumor progression by altering the Warburg effect in hepatocellular carcinoma cells." (PMID 32742447, 2020). "However, previous findings identified a specific role for the mammalian N-end rule enzyme UBR5 in degrading the gluconeogenic enzyme PCK1 under high-glucose conditions and a MAGE-TRIM28 E3 ligase complex targeting FBP1 for proteolytic degradation in a hepatocellular cancer background." (PMID 29911972, 2018). "In the present study we demonstrated that restoring the expression of FBP1 in hepatocellular carcinoma cells can also switch glycolysis to gluconeogenesis, alter energy metabolism in HCC cells and inhibit tumor growth." (PMID 28262837, 2017). "Moreover, formation of MAGE-TRIM28 ubiquitin ligase complexes was also demonstrated to promote the Warburg effect and hepatocellular carcinoma progression by targeting Fructose-1,6-biphosphatase (FBP1), a rate-limiting enzyme in gluconeogenesis, for degradation." (PMID 28851455, 2017). "In the nucleus, FBP1 was shown to directly interact with the HIF inhibitory domain to repress HIF activity in renal cancer and hepatocellular carcinoma." (PMID 34854226, 2022). "To exclude that the effects observed above are cell type specific, we additionally exposed rat hepatoma cells McA-RH7777, which are known to highly express FBP1." (PMID 36613872, 2022). "In hepatocellular carcinoma, mTOR blockade not only hindered PI3K/AKT/mTOR signal but also reduced the concentration and stability of FBP1/2, thus restraining the proliferation of hepatocellular carcinoma cells." (PMID 34568005, 2021). "Our previous study showed that the key enzyme of gluconeogenesis, FBP1, was downregulated and played an important role in regulating 18F-FDG uptake in hepatocellular carcinoma." (PMID 30723389, 2019).
hepatocellular carcinoma (continued). "Earlier we reported that FBP1 is essential for HCV replication in MH14 cells derived from Huh7 cells, an hepatocellular carcinoma cell line in which FBP1 is abundantly expressed." (PMID 25487856, 2014). "Here we report that the human FBP1 gene is regulated by two liver-enriched transcription factors, CCAAT-enhancer binding protein-α (C/EBPα) and hepatocyte nuclear factor 4α (HNF4α) in human hepatoma HepG2 cells." (PMID 29566023, 2018). "Similar findings have been observed in hepatocellular carcinoma (HCC), highlighting OGT’s crucial role in tumor growth by regulating FBP1." (PMID 39285476, 2024). "We previously identified both catalytic and non-catalytic mechanisms of FBP1-dependent tumor suppression in clear cell renal cell and hepatocellular carcinomas, and a tumor suppressive role for FBP1 has been noted for pancreatic adenocarcinoma, ER-positive breast cancer, and gastric cancer." (PMID 35123542, 2022). "Recently, fructose-bisphosphatase 1 (FBP1) has been reported to suppress epithelial-mesenchymal transition (EMT) in hepatocellular carcinoma (HCC), indicating a negative role of gluconeogenesis pathway in HCC metastasis." (PMID 34650217, 2021). "In hepatocellular carcinoma, however, LOXL2 increases HIF1 gene expression by counteracting, in an SNAI1-dependent way, the negative action of fructose-1,6-bisphosphatase (FBP1) on HIF1 gene expression, resulting in increased aerobic glycolysis and angiogenesis." (PMID 37762708, 2023). "Pan-metabolomic analysis has been used to show that the FBP1 protein was inhibited in both clear cell renal cell carcinoma (ccRCC) tumors and hepatocellular carcinomas; moreover, this disappearance was not regulated by HIF activation and exhibited the tumor-suppressive functions of FBP1." (PMID 28580187, 2017).
pancreatic cancer (30 papers, 2015 to 2025). "The BRCA2 mutation status seems to be dispensable for the effect of FBP1 on the sensitivity of pancreatic cancer to Olaparib." (PMID 34854226, 2022). "Chen etal. found that CBX3/HP1γ promoted cell cycle transition-associated tumor progression by suppressing FBP1 in pancreatic cancer." (PMID 31375643, 2019). "The reduction of FBP1 expression in pancreatic cancer tissue compared with adjacent normal tissue is associated with a poor prognosis." (PMID 30201002, 2018). "Collectively, our result indicated that JQ1 decreased the c-Myc expression partially via stabilizing FBP1 andthe loss of FBP1 contributed to JQ1 resistance in pancreatic cancer." (PMID 30201002, 2018). "At last, FBP1 was down-regulated in pancreatic tumor specimens and also associated with the prognosis of (PDAC)." (PMID 26068981, 2015). "CDK4/6-E2F1 mediates an increase in MAGED1 expression, which promotes FBP1 degradation and the Warburg effect in pancreatic cancer." (PMID 40307228, 2025). "Studies have demonstrated that FBP1 expression is positively correlated with favorable prognosis in ccRCC patients, and FBP1 was also regulated by ubiquitination in liver and pancreatic cancer." (PMID 40419474, 2025). "To identify potential downstream substrates of the E3 ubiquitin ligase TRIM47, we screened the literature and found that the ubiquitination of FBP1 by TRIM47 was involved in the carcinogenesis of pancreatic cancer." (PMID 40801794, 2025). "They found that TRIM47 expression was significantly upregulated along with the decrease of FBP1 expressions in pancreatic cancer patient tissues linking to a lower survival rate, which was also approved in pancreatic cancer cells as well." (PMID 40618019, 2025). "Nuclear FBP1 regulates pancreatic cancer sensitivity to PARP drugs by binding to DNMT1 and trapping PARP1 in chromatin." (PMID 40100307, 2025). "In pancreatic cancer, a recent study claimed that TRIM47 can accelerate aerobic glycolysis and promote tumor progression by regulating FBP1-associated ubiquitination." (PMID 40618019, 2025). "FBP1 increases the sensitivity of pancreatic cancer to gemcitabine by binding to IQGAP1, impeding IQGAP1-dependent ERK1/2 phosphorylation and activation." (PMID 40100307, 2025). "Tripartite motif 47 enhances aerobic glycolysis in pancreatic cancer by binding to and promoting the ubiquitination of FBP1." (PMID 38238754, 2024). "For instance, TRIM47 has been implicated in promoting tumor progression in colon and pancreatic cancer by degrading SMAD4 and FBP1." (PMID 38199981, 2024). "In pancreatic cancer, TRIM47 can ubiquitinate fructose-1,6-diphosphatase (FBP1) and accelerate the degradation of FBP1, so as to promote the glycolysis and proliferation of pancreatic cancer cells." (PMID 37582735, 2023). "In pancreatic cancer, TRIM47 causes ubiquitination and degradation of fructose-1, 6-biphosphatase 1 (FBP1)." (PMID 35954308, 2022). "Recently, it has been shown that the presence of the FBP1 protein increases the sensitivity of pancreatic cancer cells to the bromodomain and extraterminal domain (BET) inhibitor JQ1." (PMID 35477823, 2022). "Recently, it was shown that the presence of the FBP1 protein increases the sensitivity of pancreatic cancer cells to the bromodomain and extraterminal domain (BET) inhibitor JQ1, highlighting FBP1’s possible role in individualized cancer therapy." (PMID 35477823, 2022). "Together, these data indicated that FBP1 contributed to sensitivity to PARP1 inhibitors through the DNMT1‐PARP1 complex in pancreatic cancer." (PMID 34854226, 2022). "Since the nuclear localization of FBP1 in pancreatic cancer is crucial for the sensitivity of pancreatic cancer to PARP inhibitors, the regulatory mechanism by which FBP1 is translocated to the nucleus needs to be further studied." (PMID 34854226, 2022). "In this study, we demonstrate that FBP1 regulates the sensitivity to PARP inhibitors in pancreatic cancer." (PMID 34854226, 2022).